ERH (ERH mRNA splicing and mitosis factor)
Diseases named in the same sentence as ERH in open-access papers (continued):
Sharing a sentence is not in itself a finding about the gene and the disease.
tumor (12 papers, 2008 to 2026). "Furthermore, this expression pattern suggests that ERH might be implicated in carcinogenesis and tumour-progression and this should be further investigated in appropriately designed functional studies." (PMID 18500978, 2008). "The interaction between tumor cells and brain cells contributes to a microenvironment that supports BC growth by secreting factors such as ERH, RPA2, S100A9, and nerve growth factor inducible (VGF)." (PMID 39712454, 2025). "High expression of ERH, one of the NNMT+ tumor cell-associated genes, predicted longer survival in LUSC." (PMID 37430270, 2023). "Analyzed by co-IP and MS in 2011, ERH was shown to interact with HOTS, a tumor growth inhibitor encoded by H19 antisense transcript." (PMID 35677162, 2022). "In the two MTN sets of malignant/normal breast and ovarian tissue,ERH was clearly more abundantly expressed in all tumours than in normal tissue samples." (PMID 18500978, 2008). "ERH expression was detectable in all malignant and normal breast tissue samples, and expression was clearly stronger in all tumour samples as compared with normal tissue samples." (PMID 18500978, 2008). "We further studied the relationship between ERH and tumor cell migration and invasion." (PMID 30866868, 2019). "Other experiments suggest that ERH underexpression may constrain tumor aggressiveness, given that ERH knockdown reduces tumor cell viability through KRAS oncogene-dependent pathways." (PMID 28719635, 2017). "ERH mRNA expression in tumor tissue was higher than in the matched normal tissue (p = 9.3 × 10−37)." (PMID 25880358, 2015). "They did not clarify whether the difference in ERH expression was the cause or the result of the VHL tumor." (PMID 35677162, 2022). "The expression levels of BAX (p = 0.0017), ERH (p = 0.0067), APC (p = 0.0416), and CNBP (p = 0.0244) were significantly higher in tumor tissues of the NBL group than in the control group." (PMID 35991559, 2022). "In this dataset, expression of ERH mRNA was correlated with expression of ATR mRNA in 444 liver tissues containing HCC and non-tumor tissues." (PMID 25880358, 2015). "In all of these previous studies, the relationship between the ERH gene and tumor migration and invasion was not studied." (PMID 30866868, 2019). "We hypothesized that up-regulation of DNA damage response genes such as ERH, ATR and CHK1 in HCC tumor cells could contribute toward resistance to DNA-damaging chemotherapy and inhibiting DNA damage response might thus overcome this resistance." (PMID 25880358, 2015). "Concurrently, BC cells secrete factors like ERH, RPA2, and S100A9, which are not normally present in the brain, thereby enhancing tumor proliferation." (PMID 39712454, 2025).
ERH also shares sentences with these, for which no sentence is quoted: brain medulloblastoma (1 paper); lung adenocarcinoma (1); lupus (1); melanoma (1); thrombosis (1).